OR7A17 (olfactory receptor family 7 subfamily A member 17)
Description:
Odorant receptor.
Synonyms: HTPCRX19; BC85395_4
Tractability: Antibody: UniProt places it where antibodies can reach, with medium confidence; UniProt predicts a signal peptide or a membrane-spanning region; its Gene Ontology location is reachable by antibodies, with medium confidence.
Gene: Protein-coding gene on chromosome 19 (14,878,203 to 14,886,132, reverse strand). Ensembl gene ENSG00000185385.
Subcellular location: Cell membrane
Pathways (Reactome):
Sensory Perception: Expression and translocation of olfactory receptors
Gene Ontology:
Molecular function: protein binding; olfactory receptor activity; G protein-coupled receptor activity
Biological process: signal transduction; detection of chemical stimulus involved in sensory perception of smell; G protein-coupled receptor signaling pathway
Cellular component: plasma membrane; membrane
Genetic constraint (gnomAD): Loss-of-function variants: 0 observed, 0.0826 expected, observed/expected ratio (o/e) 0, 90% interval 0 to 1.89. That is too few expected variants to judge how well the gene tolerates losing a copy. Missense variants: 364 observed, 369.14 expected, observed/expected ratio (o/e) 0.99, 90% interval 0.9 to 1.08. Synonymous variants: 155 observed, 145.2 expected, observed/expected ratio (o/e) 1.07, 90% interval 0.94 to 1.22.
Homologues: Orthologues: dog OR7A23 (78% identical), dog OR7A26 (77% identical), dog OR7A53 (77% identical), dog OR7A52 (77% identical), dog OR7A54 (76% identical), mouse Or7a40 (76% identical), dog OR7A58 (76% identical), dog OR7A69 (76% identical), dog OR7A60 (75% identical), dog OR7A74 (75% identical), rat Or7a36 (74% identical), mouse Or7a36 (74% identical), and 4 more. Paralogues in human: OR7A10 (83% identical), OR7A5 (80% identical), OR7D4 (68% identical), OR7C1 (68% identical), OR7C2 (66% identical), OR7G2 (65% identical), OR7E24 (64% identical), OR7D2 (64% identical), OR7G3 (63% identical), OR7G1 (60% identical), OR1G1 (57% identical), OR1E1 (54% identical), and 116 more.
Diseases named in the same sentence as OR7A17 in open-access papers:
OR7A17 is named in the same sentence as 3 diseases in open-access papers, as found by Europe PMC text mining. Sharing a sentence is not in itself a finding about the gene and the disease.
OR7A17 shares sentences with these, for which no sentence is quoted: atopic dermatitis (1 paper); leukemia (1); skin disorder (1).